CD209 (CD209 molecule)
Diseases named in the same sentence as CD209 in open-access papers (continued):
Sharing a sentence is not in itself a finding about the gene and the disease.
dyslipidemia (1 paper, 2020). "In particular, the CD209 protein could be a secreted protein, released by M2 macrophages from adipose tissue, with a beneficial role in controlling lipid levels, thereby possibly protecting from developing dyslipidemia and related metabolic complications; see S4 Appendix for further discussion." (PMID 32492067, 2020).
fungal keratitis (1 paper, 2018). "Two SNPs of CD209 encoding DC-SIGN (rs735239 and rs735240) are associated with a higher susceptibility to fungal keratitis in the northern Han Chinese population." (PMID 29915598, 2018).
Hypertension (1 paper, 2018). The presence of chronic increased pressure in the systemic arterial system. "Thus, surface expression of CD209 and CD83 may have functional consequences in enhancing immunogenicity of monocyte-derived cells in hypertension." (PMID 29800237, 2018).
Insulin resistance (1 paper, 2022). Increased resistance towards insulin, that is, diminished effectiveness of insulin in reducing blood glucose levels. "LECT2 stimulates inflammatory response and insulin resistance in adipocytes via CD209/P38 dependent pathway." (PMID 35656863, 2022).
juvenile idiopathic arthritis (1 paper, 2017). Juvenile idiopathic arthritis (JIA) is the term used to describe a group of inflammatory articular disorders of unknown cause that begin before the age of 16 and last over 6 weeks. "In juvenile idiopathic arthritis, CD209+ cells were increased in peripheral blood and accumulated in synovial fluid." (PMID 28377641, 2017).
leukoplakia (1 paper, 2024). A white patch or plaque on a mucous membrane that cannot be characterized clinically or pathologically as any other disease. "Finally, we found that the myeloid cells subgroup in the HNSCC group highly expressed the marker genes of M2 macrophages such as CD163 and CD209, indicating that the tumor promoting effect of myeloid cells in the HNSCC group was stronger than that of leukoplakia." (PMID 38582791, 2024).
Lewis lung carcinoma (1 paper, 2014). "By applying the in vivo hypoxia model, the results suggest that intermittent hypoxia significantly promotes the metastasis of Lewis lung carcinoma (LLC), accompanied with more CD209+ macrophages infiltrated in primary tumor tissue." (PMID 25313135, 2014).
liver inflammation (1 paper, 2020). "Together, these data suggest that CD209 and sialidases function to regulate adipose and liver tissue inflammation, and that CD209 ligands and sialidase inhibitors are potential therapeutics for steatosis and liver inflammation." (PMID 33378413, 2020).
malaria (1 paper, 2020). Malaria is a serious and sometimes fatal disease caused by a parasite that commonly infects a certain type of mosquito which feeds on humans. "The genotypic frequencies of STAT6, CD28 and CD209 gene promoter polymorphisms in malaria patients were compared to the control group with logistic regression analysis." (PMID 31979279, 2020). "Our results confirm this observation, indicating that mutation of the CD209 gene has a considerable impact on malaria pathogenesis." (PMID 31979279, 2020). "The linkage disequilibrium (LD) analysis showed the strongest association between CD28 (rs35593994) and CD209 (rs4804803) gene polymorphisms in the malaria group (0.77; p = 0.0022)." (PMID 31979279, 2020). "The opposite was the case among those with the CD209 gene homozygous dominant variant (-383A/A) (20.7% versus 52.1% for the malaria and control groups, respectively)." (PMID 31979279, 2020). "The majority of malaria-infected children had the homozygous mutant variant (rs4804803G/G), while the control (uninfected) individuals predominantly had the wild type phenotype (rs4804803A/A), confirming our hypothesis that the CD209 gene is a susceptibility factor for clinical malaria." (PMID 31979279, 2020). "To answer these questions, we evaluated the genetic variability of CD209 (rs4804803), CD28 (rs35593994) and STAT6 (rs3024974) single nucleotide polymorphisms among malaria-infected children in Nigeria and extrapolated any association with markers of infection." (PMID 31979279, 2020). "We genotyped blood samples collected from a total of 561 individuals (231 malaria-infected patients and 330 uninfected, control individuals) for STAT6 (rs3024974), CD28 (rs35593994) and CD209 (rs4804803) gene polymorphisms using Taqman SNP genotyping assays." (PMID 31979279, 2020). "Our data suggest that CD209 (rs4804803) is a susceptibility factor for clinical malaria that also influences disease pathogenesis, but not CD28 (rs35593994) or STAT6 (rs3024974)." (PMID 31979279, 2020). "Our results show significant differences in genotypic frequencies between malaria and control groups for CD28 (rs35593994; p = 0.0001) and CD209 (rs4804803; p = 0.0001) but not STAT6 (rs3024974; p = 0.30) gene polymorphisms." (PMID 31979279, 2020).
metastatic disease (1 paper, 2023). "In this study, these groups were associated with different clinical outcomes, and CD68/CD163/CD209-immune hotspots predicted progression to metastatic disease and cancer-specific survival." (PMID 37190147, 2023). "In our cohort, CD68/CD163/CD209-immune hotspots predicted progression to metastatic disease and cancer-specific survival." (PMID 37190147, 2023).
multiple sclerosis (1 paper, 2023). A progressive autoimmune disorder affecting the central nervous system resulting in demyelination. "For instance, in a mouse model of multiple sclerosis, TGF-β and GM-CSF secreted by the BBB have been shown to induce the differentiation of CD14+ BBB-bound monocytes towards CD83+CD209+ DCs." (PMID 36495563, 2023).
Opportunistic infection (1 paper, 2024). An infection that is caused by a pathogen that would generally not be able to cause an infection in a host with a normal immune system. "CD209 and its downstream Lys1, induced by ecdysone, contribute to gut homeostasis, thereby minimizing the risk of opportunistic infections." (PMID 38448930, 2024). "We elucidated the essential role of a CD209 (CTL) − Lys1 (Lys) immune function in maintaining gut homeostasis, thereby minimizing the risk of opportunistic infections during complete metamorphosis." (PMID 38448930, 2024).
prostate tumors (1 paper, 2023). "Immunohistochemical analyses were performed to identify CD209+ (immature DC), CD83+ (mature DC), CD68+ (total MΦ) and CD163+ (M2-type MΦ) cells in the 99 prostate tumors." (PMID 37435060, 2023).
small cell lung carcinoma (1 paper, 2024). Small cell lung cancer (SCLC) is a highly aggressive malignant neoplasm, accounting for 10-15% of lung cancer cases, characterized byrapid growth, and early metastasis. "In small cell lung cancer, M1 macrophages are up-regulated in the CD209-High group." (PMID 38612764, 2024).
infection (369 papers, 2005 to 2026). The state of being infected such as from the introduction of a foreign agent such as serum, vaccine, antigenic substance or organism. "A recent genomic study in Iberian pigs proposed CD209 as a good candidate gene due to its association with immune defense and modulation during infection by pathogens." (PMID 35355298, 2022). "In summary, CD209 was expressed abundantly in various healthy human tissues, especially in adipose tissue, small intestine, and lymph nodes, which had higher susceptibility to infection by SARS-CoV-2." (PMID 35783255, 2022). "Overall, the CD209 (rs4804803) gene polymorphism presenting the mutant allele G is critical in determining disease susceptibility, thereby identifying this gene and its polymorphism (A > G; rs4804803) as an important driver of immune response during infection." (PMID 31979279, 2020). "CD209 gene promoter polymorphism has been shown to be associated with susceptibility to infection." (PMID 25755928, 2015). "A down-regulation of the expression of CD209, a c-type lectin receptor found specifically in dendritic cells (DC), was observed only in the head-kidney of vaccinated animals early on infection in addition to the tlr9 inhibition." (PMID 37346045, 2023). "Intriguingly, adipose tissue demonstrated the abundant expression of CD209 in the GTEx and HPA public datasets, which was in line with the current concept that obese patients are more susceptible to infection by SARS-CoV-2." (PMID 35783255, 2022). "After losing the virulence plasmid, S. sonnei rough strains fail to escape from macrophages, and the CD209/hCD207-S. sonnei rough interactions most likely result in the clearance of rough S. sonnei during infection." (PMID 33591245, 2021). "Alternatively, in the context of other viruses known to directly bind CD209 as we show here for SARS-CoV-2, soluble CD209 has been demonstrated to modulate infection, such as by promoting endocytosis if the soluble CD209 coating the virus acts as opsonins." (PMID 34402426, 2021). "Understanding the T. gondii-CD209 interactions would provide a possible preventive strategy for this infection." (PMID 32391004, 2020). "Since host genetic polymorphisms have been demonstrated to be associated with vulnerability to human infection, in this study five candidate genes—ACE2, TMPRSS2, CD209, IFITM3, and MUC5B—were selected based on their relevance to the current pandemic." (PMID 33101356, 2020). "For instance, CD209-dependent viral entry and infection can initiate signaling events in host cells that compromise immune responses and promote infection of DCs." (PMID 33375175, 2020). "These seven publications indicate one fact: blockade of the interactions between the C-type lectins (CD205, CD207, CD209) and carbohydrates of bacteria inhibit bacterial interactions with the host, dissemination, and infection." (PMID 33488579, 2020). "This suggested that CD209 mainly enhanced infection of T. gondii and was a preferred target by the parasite for infection and dissemination." (PMID 32391004, 2020). "Studies on B lymphocytes and platelets indicate that CD209 expressed in these cells successfully mediate the entry of and infection by HIV-1." (PMID 33375175, 2020). "DC-SIGN (CD209) is an extensively studied receptor, due to its expression on various dendritic cell (DC) populations and its role in infection of certain viruses, like HIV." (PMID 31637232, 2019). "Flow cytometry analysisshowed that the frequency of mdDCs(CD11c+/CD14-/CD209+) infected(4G2+) with ZV BR 2015/15261 (25.54% ± 21.12) was similar to thefrequency of infection with ZIKV PE243 (27.47% ± 16.98) and ZIKV MR766 (24.84% ±20.49)." (PMID 31432892, 2019). "Collectively, the results indicate that teleost CD209 serves as a pattern recognition receptor that exerts an influence on the phagocytosis process during pathogen infections." (PMID 28869534, 2017).
infection (continued). "This was even more surprising with regards to the expression pattern of well-described host receptors for viral binding and infection DC-SIGN (CD209) and mannose receptor (CD206), which were absent on LCs." (PMID 25474532, 2014). "Genetic mutations in cell surface receptors can alter viral entry into target cells, and markers associated with altered susceptibility to infection and disease outcome with CHIKV and other Old World alphaviruses include HLA, TLR-3, TLR-7, TLR-8, MXRA8, and CD209 (DC-SIGN)." (PMID 40007016, 2025). "Taken together, our results demonstrated that B8-dIgA1- and B8-dIgA2-mediated SARS-CoV-2 infection likely involved viral capture and infection of mucosal CD209+ cells, followed by more robust trans-infection of ACE2+ epithelial cells through cell–cell transmission in NT." (PMID 37542391, 2023). "Considering that CD209+ DCs promote HIV-1 trans-infection of CD4+ T cells via cell–cell contacts, we speculated that B8-dIgA1 and B8-dIgA2 might not be able to block the similar process for SARS-CoV-2." (PMID 37542391, 2023). "In addition to ACE2, other potential SARS-CoV-2 receptors for infection are indicated, including CD209." (PMID 35783255, 2022). "In addition, our study showed that transcript abundance of cd4 (Th1 response), cd209 (innate immune response), ccr7 (Th2), and il1b (inflammation) were suppressed during the infection with sea lice alone." (PMID 35046944, 2021). "The presence of CD209 enhanced T. gondii invasion, dissemination and thus infection." (PMID 32391004, 2020). "However, in cases which HIV-1 receptor and co-receptors (CD4 and CCR5/CXCR4) are present on the host cells, CD209 can facilitate infection by transferring the virus to immune cells." (PMID 33375175, 2020). "CD209 has been proven to play important roles in the immune modulation during pathogen infection." (PMID 28869534, 2017). "CD209 is a marker expressed in earlier stages of activation and it is therefore possible that infection kinetics may have an impact." (PMID 28355218, 2017). "In addition, gp120 has been shown to interact with DC-SIGN/CD209 on the surface of dendritic cells to enhance virion transmission and infection." (PMID 27087306, 2016). "While several studies have eloquently described how HIV and COVID viruses have hijacked the normal engulfment by dendritic cells as a way of spreading infection, studies have also demonstrated that NPs binding to CD209 could act as a microbicide-inhibiting viral spread of these infections." (PMID 38593053, 2024). "In this study, we found that, in the presence of neutralizing B8-dIgA1 or B8-dIgA2 antibodies, SARS-CoV-2 might use the cellular receptor CD209 for capture or attachment, which likely expanded the use of CD209+ cells, leading to NT infection and trans-infection." (PMID 37542391, 2023). "PRRSV exhibits remarkable receptor plasticity during initial infection, engaging multiple attachment factors including heparan sulfate, vimentin, CD169 (sialoadhesin), MYH9, DC-SIGN (CD209), and CD151 for cell surface docking." (PMID 40623027, 2025). "SARS-CoV-2 engages CD209+ cells to evade ACE2-dependent neutralizing B8-dIgA1 and B8-dIgA2 for broader NT infection and injury." (PMID 37542391, 2023). "Since B8-dIgA showed the binding capacity to both CD209 and viruses, we sought to determine the effect of different B8-IgAs on human monocyte-derived dendritic cells (MoDCs)-mediated SARS-CoV-2 trans-infection of target cells." (PMID 37542391, 2023). "The most established example of this process is the infection of the human immunodeficiency virus (HIV), which is mediated by the binding of HIV gp120 protein with DC-SIGN (CD209), to facilitate the infection of CD4+ T-cells." (PMID 35401532, 2022). "CD209 (DC-SIGN) and MYH9 interacting with GP5 are essential factors in both PRRSV-1 and PRRSV-2 entry and infection." (PMID 33918746, 2021).
infection (continued). "Aside from the role of CD209 and CD209L in cis- and trans-infection and transmission, the recognition of these receptors by pathogens also can impact the host defense mechanism against these pathogens." (PMID 33375175, 2020). "In many cases lectin receptors such as CD209 and CD209L are employed as functional portals for viral recognition and infection." (PMID 33375175, 2020). "CD209L and CD209 are widely expressed in SARS-CoV-2 target organs and can contribute to infection and pathogenesis." (PMID 33375175, 2020). "Lectins, such as CD209 (DC-SIGN), can serve as attachment factors and enhance infection of certain viruses." (PMID 32106547, 2020). "Examining expression of CD209, CD206, and CCR5 following HIV capture revealed that change in surface expression of HIV capture and infection molecules varied considerably between donors and maturation conditions." (PMID 27603520, 2016). "Although both purified AMs and IMs supported the production of infectious virions, the virus enters the cells by distinct mechanisms: infection of AMs uses the canonical receptor ACE2 and CD169, whereas infection of IMs uses an ACE2-independent mechanism that relies instead on CD209." (PMID 38597954, 2024). "In support of this notion, previous studies indicated that mucosal DCs can capture HIV-1 through binding of its envelope glycoproteins to CD209 and efficiently transfer the bound virions to CD4+ T cells, in a process called trans-enhancement or trans-infection." (PMID 37542391, 2023). "Following an infection or inflammation, monocytes were thought to differentiate into inflammatory DC (moDCs/InfDCs) —expressing monocyte (CD14, CD16) and DC (MR/CD206, DC-SIGN/CD209) markers—capable of acting in situ at the inflammation site (low migratory capacity)." (PMID 37190135, 2023). "For one of the targets (CD209), although we experimentally demonstrate binding of CD209 with spike protein of SARS-CoV-2, understanding the functional significance CD209 has on viral entry and any immunological relevance during infection requires further research." (PMID 34402426, 2021). "Similarly, CD209 and CD209L interact with Ebola virus glycoprotein and mediate infection of endothelial cells via both cis- and trans-infection." (PMID 33375175, 2020). "Previous studies on SARS-CoV demonstrated a direct role for CD209L and CD209 in infection by acting as entry receptors for SARS independent of ACE2." (PMID 33375175, 2020). "APCs express at least three immunoreceptors that belong to the calcium-dependent (C-type) lectin family: DC-specific intercellular adhesion molecule 3 grabbing non integrin (DC-SIGN, CD209), DEC-205 (CD205), and Langerin (CD207), which can be utilized by pathogens to initiate infection." (PMID 32391004, 2020). "SARS-CoV utilizes ACE2, CD209, CLEC4G, and CLEC4M for its infection to host." (PMID 33330620, 2020). "We also observed increased level of expression of DC-SIGN (dendritic cell-specific ICAM-3 grabbing non-integrin; also designated as CD209) upon infection of BMM with HN878 compared to CDC1551." (PMID 22280836, 2012). "Since none of the B8-based MAbs could prevent SARS-CoV-2 cell-to-cell transmission, even at high concentrations in vitro, virus-laden mucosal CD209+ cells might trans-infect ACE2+ cells through cell-to-cell contacts in NT, resulting in broader infection and injury." (PMID 37542391, 2023). "Meanwhile, the capture of CD209 viruses in macrophages and dendritic cells can lead not to the infection of these cells but the utilization of viral particles, whereas in other cases, it leads to the infection of T-lymphocytes in contact with macrophages." (PMID 35163638, 2022). "Therefore the lack of CD209 or its blockade protected the liver from severe pathological effects of T. gondii and provided optimal resistance to the infection." (PMID 32391004, 2020).
infection (continued). "The C-type lectin receptors (CLRs) DC-SIGN (CD209) and L-SIGN (CD209L) enhance IAV infection however it is not known if they act as attachment factors, passing virions to other unknown receptors for virus entry, or as authentic entry receptors for CLR-mediated virus uptake and infection." (PMID 26763587, 2016). "For example, C-type lectins such as DC-specific intercellular adhesion molecule 3 (ICAM3)-grabbing non-integrin (DC-SIGN; CD209) and liver/lymph node-SIGN (L-SIGN; CLEC4M) are sufficient to enable MARV glycoprotein-mediated infection." (PMID 40333058, 2025). "For instance, E glycosylation facilitates the infection of cells expressing C-type lectin dendritic-cell-specific intercellular adhesion molecule-3-grabbing nonintegrin (DC-SIGN, also named CD209), thus contributing to ZIKV pathogenesis." (PMID 38137537, 2023). "DC-SIGN (dendritic cell specific ICAM-grabbing nonintegrin, CD209) and L-SIGN (DC-SIGN related, CD209L) are c-type lectins, which have been suggested to play a role in HCV transmission and infection." (PMID 29140443, 2018). "In addition, CD209, which is also named DC-SIGN, showed non-significant changes during infection (p > 0.05)." (PMID 18811943, 2008). "The specific EVs surface marker characterization (CD49e, CD209, CD69, CD142, and CD20) allowed for the drawing of a defined EV signature, useful to discriminate between patients negative for SARS-CoV-2 who experienced infection symptoms and those with positive clinical status of the infection." (PMID 37896755, 2023).